TIMP2 (TIMP metallopeptidase inhibitor 2)
Diseases named in the same sentence as TIMP2 in open-access papers (continued):
Sharing a sentence is not in itself a finding about the gene and the disease.
hepatocellular carcinoma (22 papers, 2012 to 2026). A malignant tumor that arises from hepatocytes. "For example, TIMP2 (tissue inhibitor of metalloproteinases 2) blockade by HIF-1α/miR-210/HIF-3α feed circuit often plays a significantly role in regulating hepatocellular carcinoma (HCC) metastasis, which is regard as associated with poor prognostic effects." (PMID 33109235, 2020). "Activation of the C19MC miR-519d was shown to target CDKN1A/p21, PTEN, AKT3 and TIMP2, and is closely associated with the pathogenesis of hepatocellular carcinoma by promoting cell proliferation and invasion, and in inhibiting apoptosis." (PMID 28270145, 2017). "TIMP-1 overexpression is associated with hepatocellular carcinoma (HCC) lung metastases, while TIMP-2 expression is downregulated in patients with HCC." (PMID 38067256, 2023). "This microRNA also manifests antiproliferative properties against hepatocellular carcinoma cells, concomitantly reducing cellular steatosis and fibrosis by targeting PPARα and TIMP2." (PMID 41523988, 2026). "Second, TACE enhances the expression of the metastasis suppressor genes nm23-H1 and TIMP-2, possibly inhibiting the metastasis of hepatocellular carcinoma." (PMID 38336712, 2024). "Upregulation of TIMP-1 and TIMP-2 led to inhibition of cell migration and invasion in hepatocellular carcinoma cells." (PMID 31726667, 2019). "The study in hepatocellular carcinoma demonstrated that the HIF-1α/miR-210/HIF-3α feedback circuit plays a regulatory role in TIMP2 suppression." (PMID 29953500, 2018). "Based on the expression status of GRP78, MMP-2, MMP-9, MMP-14 and TIMP-2 in hepatocellular carcinoma cell lines SMMC7721 and HepG2, we choose SMMC7721 to establish the in vitro invasion model for further research." (PMID 22546345, 2012). "Interestingly, in human hepatocellular carcinoma (HCC) samples, downregulation of TIMP2 expression was significantly associated with liver invasion and poorer survival outcomes." (PMID 31836008, 2019). "However, later studies implicated that miR-519d also targeted several tumor suppressors, including CDKN1A/p21, PTEN and TIMP2, and thus potentially exerted oncogenic property in hepatocellular carcinoma development." (PMID 27006642, 2016). "In hepatocellular carcinoma (HCC) cells, the expression of TIMP2 is suppressed if HIF is activated in a hypoxic environment." (PMID 37710084, 2023). "Particular attention has been paid to the imbalance between MMP-2 and TIMP-2 in hepatocellular carcinoma (HCC), and cervical, bladder, breast, and oral cancers." (PMID 32751899, 2020). "For example, MiR-519d had oncogenic roles in hepatocellular carcinoma and it targeted CDKN1A/p21, PTEN and TIMP2, which had important roles in atherosclerosis." (PMID 25333956, 2014). "We choose hepatocellular carcinoma cell line SMMC7721 for the establishment of in vitro invasion and metastasis model according to the expression levels of GRP78, MMP-2, MMP-9, MMP-14 and TIMP-2." (PMID 22546345, 2012). "Human hepatocellular carcinoma cell line SMMC7721 and HepG2 were cultured in DMEM supplemented with 10% FBS, RT-PCR and western blot were used to detect the endogenous expression of GRP78, MMP-2, MMP-9 and TIMP-2 in SMMC7721 and HepG2." (PMID 22546345, 2012). "In experiments with human hepatocellular carcinoma (HCC) cell lines HepG2 and SMMC-7721, treatment with varying concentrations of ART resulted in a decreased expression of MMP2 and an upregulation of TIMP2, which is an inhibitor of MMP2." (PMID 40001571, 2025).
chronic kidney disease (19 papers, 2013 to 2026). Impairment of the renal function secondary to chronic kidney damage persisting for three or more months. "Several studies have shown elevated levels of MMP-2 and TIMP-2 in the serum of patients with chronic kidney disease (CKD)." (PMID 33419373, 2020). "The highest concentrations of TIMP-1 and TIMP-2 were observed in end-stage renal disease patients and the lowest in I/II CKD patients." (PMID 25145866, 2014). "Patients who had chronic kidney disease had higher levels of TIMP2 (33,453.5 pg/mL, p = 0.043)." (PMID 41009516, 2025). "In individuals with MM, serum transgelin, U IGFBP-7/creatinine and U TIMP2/creatinine ratios may have utility as biomarkers of predicting advanced chronic kidney disease stages." (PMID 38708150, 2024). "The serum levels of MMP-2 and TIMP-2 are elevated in chronic kidney disease patients." (PMID 37867197, 2023). "Moreover, MMP-2 and TIMP-2 concentrations were much higher in patients with chronic kidney disease, suggesting that these factors may be involved in the pathogenesis of CAD in patients with CKD." (PMID 25145866, 2014). "This prospective observational study aimed to validate and measure TIMP‐2 and IGFBP7 in urine of dogs and to compare these values between healthy dogs, dogs with AKI, dogs with chronic kidney disease (CKD) and critically ill (CI) dogs." (PMID 38053473, 2023). "Statistically significant results were found also for the MMP-2/TIMP-2 ratio, with the lowest values in the control group and the highest in patients with stage IV chronic kidney disease as well as in patients with stage V CKD and on dialysis." (PMID 26843213, 2016). "Assess whether NGAL and TIMP‐2 at admission (T0) and 24 h later (T1) identify survival in critically ill (CI) and AKI dogs, development of hospital‐acquired AKI in CI dogs, and development of chronic kidney disease (CKD) in AKI dogs after 3 months." (PMID 40008829, 2025). "We also examined the performance of urine [TIMP-2]·[IGFBP7] compared to various other markers including urine KIM-1 and urine NGAL in terms of discrimination between AKI of different severities and various non-AKI conditions including chronic kidney disease." (PMID 23388612, 2013).
kidney damage (18 papers, 2015 to 2025). "Baseline elevations in TIMP-2 caused by these diseases may conceal acute alterations associated with kidney damage." (PMID 39001241, 2024). "TIMP-2 is an important modulator of extracellular matrix turnover and contributes to several physiological and pathological processes, including kidney damage and healing." (PMID 41155766, 2025). "Accordingly, the development and validation of novel kidney damage/stress biomarkers such as (TIMP-2) × (IGFBP7) has been driven forward in recent years." (PMID 39021823, 2024). "Although TIMP-2 is a marker for cell cycle arrest, which can suggest kidney damage early on, its precise role in the pathogenesis of AKI remains uncertain." (PMID 39001241, 2024). "Urinary tissue inhibitor of metalloproteinase-2 (TIMP2) and insulin-like growth factor-binding protein 7 (IGFBP7), both early markers of kidney damage, are closely associated with the G1 cell cycle arrest that occurs during the very early phases of AKI." (PMID 34681750, 2021). "Recent studies reported on the discovery and validation of two urinary G1 cell cycle arrest biomarkers for early diagnosis of kidney damage: tissue inhibitor of metalloproteinase-2 (TIMP-2) and insulin-like growth factor-binding protein 7 (IGFBP7)." (PMID 26606754, 2015). "This pathway demonstrates an unique mechanism by which TIMP-2 leads to kidney damage." (PMID 39001241, 2024). "Other biomarkers of kidney damage, such as [TIMP2]*[IGFBP7] or NGAL may be able to identify and quantify kidney stress or damage early on in the course of AKI, but are likely of limited value for peri-RRT assessment of kidney recovery." (PMID 36316692, 2022). "The main causes may be that TIMP-2 and IGFBP7, reflecting the stress status of the kidney, are more relevant to kidney damage." (PMID 28340605, 2017). "In general, a combination of the biomarkers (urinary TIMP-2 and IGFBP7) for the early detection of perioperative kidney damage and accelerated intervention schemes seems to be the basis for AKI prophylaxis and treatment in surgical settings." (PMID 36614838, 2022). "In this study, we only investigate two kidney damage markers for AKI prediction and cannot compare the prediction performances of these biomarkers with other reported AKI prediction markers, such as NGAL and TIMP2." (PMID 41301775, 2025). "The findings of this study suggest that using [TIMP2]*[IGFBP7] at 12 h could lead to the early detection of severe AKI, prompting additional clinical action to hinder further kidney damage." (PMID 36673127, 2023). "Urinary TIMP-2 and IGFBP7 concentrations are considered to be markers of kidney damage." (PMID 32487237, 2020). "uNGAL is a marker of tubular injury and its concentration rises immediately after AKI, while the proteins TIMP-2 and IGFBP7 jointly participate in the G1 phase cell cycle arrest processes and their tubular expression and urinary excretion increase in response to kidney damage." (PMID 40025594, 2025). "Further, in contrast to recently developed damage biomarkers such as TIMP2•IGFBP7, suPAR’s direct pathophysiological involvement and long-lasting kinetics provide robust, longitudinal information on the activity of kidney tissue inflammation, kidney damage, and prognosis in SI-AKI." (PMID 37036003, 2023). "The use of TIMP2 × IGFBP7 biomarkers at admission could, therefore, be helpful in the trauma setting, where implementation of an AKI care bundle to prevent or interrupt the mitigation of kidney damage is possible." (PMID 36292170, 2022).
Obesity (18 papers, 2010 to 2025). Accumulation of substantial excess body fat. "In addition to TIMP2 deficiency-induced neuromotor deficit and defective myogenesis, TIMP2−/−, both male and female, mice exhibit obesity with a relatively preserved glucose tolerance and insulin sensitivity." (PMID 37445827, 2023). "ITIH4 and TIMP2 have been characterized as obesity-associated genes in human." (PMID 31235755, 2019). "TIMP-1 and TIMP-2 plasma levels are increased in patients with metabolic syndrome and their levels correlate with obesity indices including BMI, waist circumference and metabolic parameters." (PMID 38541059, 2024). "TIMP2 has been shown to be a human obesity-related gene that inhibits the role of metalloproteinases in adipocyte differentiation." (PMID 39272234, 2024). "It has been reported that TIMP-2 mediates endothelial proliferation, formation of a capillary tube in obesity, and promotes tumor invasion in advanced squamous cell carcinomas by activating the ERK/MAPK signaling pathway." (PMID 35022331, 2022). "Among these TIMPs, especially TIMP-1 and TIMP-2 gain importance in obesity-related cardiovascular diseases." (PMID 34625635, 2021). "Hepatic TIMP1 and TIMP2 levels are elevated in obesity-related non-alcoholic fatty liver disease (NAFLD), and TIMP1 has been shown to mediate HFD-induced hepatic steatosis in mice." (PMID 28740132, 2017). "The RT-PCR analysis showed major changes between both groups with an elevated mRNA level of growth factors, aggrecan and TIMP-2 in chondrocytes from obese patients suggesting that the chondrocyte metabolic activity is increased with obesity." (PMID 20534145, 2010). "TIMP2 promotes intramuscular fat deposition in the muscle of chickens via the ECM receptor interaction signaling pathway, while LOX accelerates collagen fibril cross-linking associated with obesity and fibrosis progression." (PMID 40723406, 2025). "RYGB contributes significantly to weight loss, improved BMI, reduced FM, and reduced TIMP2 expression in PBMCs, which might contribute to the ECM remodeling in the obesity and could be useful as a circulating biomarker." (PMID 34722599, 2021). "Although the balance between TIMP2 and MMP2 seemed essential for ECM remodeling, we demonstrated that decreased TIMP2 expression in PBMC could be a marker of improvement of obesity after 6 months of RYGB." (PMID 34722599, 2021). "Such overexpression of TGFβ, IGF-1 and TIMP-2 has been previously reported in subcutaneous adipose tissue from obese individuals indicating that chondrocytes may also exhibit an obesity-related gene expression pattern." (PMID 20534145, 2010). "In addition, the BMI-dependent effect of leptin for the expression of TIMP-2 and MMP-13 may explain why obesity is associated with an increased risk for OA." (PMID 20534145, 2010). "The enrichment analyses highlighted the interaction between TIMP2 and MMP2 genes and the molecular pathways involving the ECM remodeling in the obesity condition." (PMID 34722599, 2021). "Age, obesity, and previous cardiac disease were significantly associated with incidence of AKI, whereas the shock index, ISS, and TIMP2 × IGFBP7 values were not." (PMID 36292170, 2022). "Our results exhibited that TIMP-2 levels were significantly increased in people with obesity and overweight compared to non-obese people." (PMID 34625635, 2021). "Subdividing people with obesity into MetsO and MHO, a negative correlation was also detected between MMP-2 levels, MMP-2/TIMP-2 ratio and CRP values in MetsO (r = − 0.26, p = 0.03, r = − 0.27, p = 0.03, respectively)." (PMID 34625635, 2021).
Hypertension (17 papers, 2009 to 2025). The presence of chronic increased pressure in the systemic arterial system. "Risk factors for AKI development were male sex, history of hypertension, low albumin levels, and high [TIMP-2]⋅[IGFBP7] and NGAL levels." (PMID 39982587, 2025). "TIMP-2 gene polymorphisms have been studied in several diseases such as hypertension, Achilles tendon pathologies, cancer, and varicose vein." (PMID 27901480, 2017). "In this study, also a correlation between higher levels of metalloproteinase MMP-2 as well as higher values of MMP-2/TIMP-2 ratio and the prevalence of arterial hypertension was observed." (PMID 26843213, 2016). "AngII hypertension was associated with significant increases in aortic wall to lumen ratio (∼29%), collagen deposition (∼14%) and expression of TIMP1 and TIMP2." (PMID 24205262, 2013). "We found increased levels of TIMP-2 in amniotic fluid of women who eventually developed a hypertensive disorder compared with normotensive women." (PMID 19698156, 2009). "The level of TIMP-2, however, was significantly higher in women who developed a hypertensive disorder, compared with normotensive women (2277 ± 135 versus 1043 ± 92 optical density, respectively; P < 0.01)." (PMID 19698156, 2009). "Mean amniotic fluid MMP-2 and TIMP-2 levels were significantly higher in women who developed a hypertensive disorder compared to normotensive women (P < 0.0004 and P < 0.01, respectively)." (PMID 19698156, 2009). "TIMP-2 levels are higher in women who develop a hypertensive disorder; however, the specific role of TIMP-2 in the disease is still unknown." (PMID 33419373, 2020). "Moreover, we had a number of suggestive genes arise from our vascular tissue data, highlighted as having specific effects on the ECM including TIMP2, PSAP, FN1, VCAN, and LOX, each of which have been previously implicated in hypertension." (PMID 30931314, 2019). "Immunodetection of renal cortical tissue extracted protein revealed that in Ang II induced hypertension, the expression of MMP-2 and -9 were upregulated whereas, their inhibitory molecules TIMP-2 and -4 were diminished." (PMID 24386282, 2013). "Collectively, these data support the idea that the proteasome is critically involved in controlling the balance of TIMP1/TIMP2 expression and MMP2 activity which in turn modulates aortic extracellular matrix turnover in hypertension." (PMID 24205262, 2013). "In VSMCs, CRID3 inhibited collagen synthesis induced by Ang II and CRID3 prevented the increased expression of MMP2 and MMP9 unlike TIMP2, indicating that suppressing NLRP3 inflammasome was a target in aortic fibrosis in hypertension." (PMID 30906225, 2019).
myopia (17 papers, 2014 to 2025). "MMP2 and TIMP2 have long been associated with myopia and our previous data showing that their distribution was changed after dark-rearing." (PMID 39607017, 2024). "The development of myopia has been associated with a mean reduction in TIMP2 (OMIM:188825) mRNA expression, a variant of which was present in family OFT-00209." (PMID 35457050, 2022). "Among the MMP isoforms, it has been consistently reported that elevated MMP2 activity is associated with myopia in animal studies, although less is known regarding their inhibitory regulator TIMP2 and related molecules such as TGF-β." (PMID 34698138, 2021). "Further, we investigated the changes of PIK3R3, AKT2 and TGF-β1, E-cadherin, COLI, BCL-2, BAD, MMP2, and TIMP2 in the sclera of myopic guinea pigs to explore their effects on the development of myopia after 2- and 4-week myopic induction." (PMID 40216914, 2025). "After intravitreal injection of rhBMP2, compared with the myopia group, TIMP2 and Col1A1 expression was significantly increased in the MD and HD groups (p < 0.05), while there was no significant change in the LD group (p > 0.05)." (PMID 40375931, 2025). "In animal models of myopia, preventing collagen damage with TIMP-2 reduced scleral collagen degradation and development of myopia." (PMID 38069354, 2023). "Many investigators believe that MMPs and TIMPs, particularly MMP-2 and TIMP-2, are potential targets to inhibit myopia development." (PMID 32596291, 2020). "Recent study showed that downregulation of MMP2 expression levels and increased TIMP2 levels accompanied the pirenzepine-induced suppression of myopia in guinea pig44." (PMID 28900109, 2017). "Besides, MMP-2 and tissue inhibitor of metalloproteinase 2 (TIMP-2) produced by fibroblast are closely related to the ECM degradation of sclera during myopia progression." (PMID 41169617, 2025). "In tree shrews, exogenous addition of TIMP-2 significantly reduced myopia development." (PMID 32596291, 2020). "Further studies are needed to identify the role of TIMP-2 in Shh-mediated experimental myopia." (PMID 24810957, 2014). "After myopia induction for 2 and 4 weeks, the expression of PIK3R3, AKT2, BAD, BCL-2, TGF-β1, E-cadherin, COLI, MMP2, and TIMP2 was detected by qPCR." (PMID 40216914, 2025). "In this study, we found that after 2 and 4 weeks of myopia induction, the expression of TGF-β1, COLI, and TIMP2 decreased compared with the levels of normal guinea pigs, whereas the expression of E-cadherin and MMP2 increased." (PMID 40216914, 2025). "After 2- and 4-week myopia induction, the MMP2 and TIMP2 expression in scleral tissues in the right eyes from the NC and LIM groups were detected by ELISA." (PMID 40216914, 2025). "Activation of the PI3K/AKT pathway regulates factors like TIMP-2 and MMP-2, which are involved in scleral remodeling and affect the axial length of the eye, contributing to myopia progression." (PMID 40933557, 2025). "The negative correlation of MMP-2, and corresponding positive correlation with TIMP-2, with choroidal thickness seen in our study suggests that this postulated degradation of Bruch’s membrane may also be related to the progressive thinning of the choroid seen in eyes with high myopia and MMD." (PMID 31673022, 2019). "For example, the two key indicators for myopia development, the vitreous chamber depth and spherical-equivalent refractive error, showed moderate correlations with the mRNA levels of MMP2 and TIMP2 genes in the superior scleral." (PMID 28900109, 2017). "Here we presented the changes in mRNA expression levels of three genes (MMP2, TIMP2, and TGFB2), all known to participate in extracellular matrix organization, at five regions of the cornea and sclera in chickens developing high myopia and astigmatism induced by form deprivation." (PMID 28900109, 2017).